HAO1 (hydroxyacid oxidase 1)
Description:
Broad substrate specificity (S)-2-hydroxy-acid oxidase that preferentially oxidizes glycolate. The glyoxylate produced by the oxidation of glycolate can then be utilized by alanine-glyoxylate aminotransferase for the peroxisomal synthesis of glycine; this pathway appears to be an important step for the detoxification of glyoxylate which, if allowed to accumulate, may be metabolized to oxalate with formation of kidney stones. Can also catalyze the oxidation of glyoxylate, and long chain hydroxyacids such as 2-hydroxyhexadecanoate and 2-hydroxyoctanoate, albeit with much lower catalytic efficiency. Active in vitro with the artificial electron acceptor 2,6-dichlorophenolindophenol (DCIP), but O2 is believed to be the physiological electron acceptor, leading to the production of H2O2. Is not active on L-lactate and 2-hydroxybutanoate.
Synonyms: HAOX1; GO; GOX; GOX1
Tractability: Small molecule: a structure with a bound ligand is known; a high-quality ligand is known; it has a binding pocket of medium quality; it belongs to a druggable protein family. PROTAC: ubiquitination databases record sites on it; its protein half-life has been measured; a small molecule that binds it is known.
Target class: Enzyme; Oxidoreductase
Gene: Protein-coding gene on chromosome 20 (7,882,985 to 7,940,520, reverse strand). Ensembl gene ENSG00000101323.
Subcellular location: Peroxisome matrix
Subcellular location (Human Protein Atlas): Vesicles
Pathways (Reactome):
Metabolism: Glyoxylate metabolism and glycine degradation
Protein localization: Peroxisomal protein import
Gene Ontology:
Molecular function: (S)-2-hydroxy-acid oxidase activity; FMN binding; glyoxylate oxidase activity; alcohol oxidase activity; oxidoreductase activity
Biological process: fatty acid alpha-oxidation; glycolate catabolic process; fatty acid oxidation; glycine biosynthetic process; response to oxidative stress
Cellular component: peroxisomal matrix; cytosol; peroxisome
Genetic constraint (gnomAD): Loss-of-function variants: 14 observed, 17.95 expected, observed/expected ratio (o/e) 0.78, 90% interval 0.51 to 1.22. The upper end of that interval is the gene's LOEUF score, 1.22, which puts it in group 5 of 6, group 1 being the genes least tolerant of losing a copy. Missense variants: 249 observed, 248.82 expected, observed/expected ratio (o/e) 1, 90% interval 0.9 to 1.11. Synonymous variants: 91 observed, 94.11 expected, observed/expected ratio (o/e) 0.97, 90% interval 0.81 to 1.15.
Homologues: Orthologues: chimpanzee HAO1 (100% identical), macaque HAO1 (99% identical), pig HAO1 (92% identical), dog HAO1 (91% identical), mouse Hao1 (89% identical), rat Hao1 (89% identical), guinea pig HAO1 (87% identical), rabbit HAO1 (85% identical), tropical clawed frog hao1 (71% identical), zebrafish hao1 (68% identical). Paralogues in human: HAO2 (45% identical), CARNS1 (25% identical).
Diseases named in the same sentence as HAO1 in open-access papers:
HAO1 is named in the same sentence as 31 diseases in open-access papers, as found by Europe PMC text mining. Sharing a sentence is not in itself a finding about the gene and the disease. The quoted sentences say what the papers report.
primary hyperoxaluria type 1 (12 papers, 2014 to 2025). A rare disorder of glyoxylate metabolism characterized by the accumulation of oxalate due to a deficiency of the peroxisomal hepatic enzyme L-alanine: glyoxylate aminotransferase (AGT). "To address these concerns, we explored the use of AAV-delivered paired Staphylococcus aureus nickases (D10ASaCas9) to target the Hao1 gene for the treatment of primary hyperoxaluria type 1 (PH1)." (PMID 38182795, 2024). "Indications in other therapeutic areas involving hepatic targets, like cardiovascular, gastrointestinal, and genitourinary (like lumasiran, which targets hepatic HAO1 to treat primary hyperoxaluria type I), were also frequently found in our analysis." (PMID 35213992, 2022). "Lumasiran (OXLUMO) or ALN-GO1 is the third siRNA drug approved by the U.S. FDA for the treatment of primary hyperoxaluria type 1 (PH1)-a rare genetic disorder that targets hydroxy acid oxidase 1 (HAO1)." (PMID 35352626, 2022). "Deficiency of glycolate oxidase (HAO1), another enzyme in the glyoxylate pathway, results in asymptomatic isolated glycolic aciduria without any apparent related abnormalities." (PMID 35055190, 2022). "Lumasiran targets hydroxyacid oxidase 1 (HAO1) for the treatment of primary hyperoxaluria type 1 (PH1), which is a rare inherited disorder characterised by the overproduction of oxalate." (PMID 33821570, 2021). "HAO1 inhibition is a potential chronic therapeutic approach for a devastating metabolic disease (primary hyperoxaluria type 1, PH1)." (PMID 32207686, 2020). "In a mouse model of primary hyperoxaluria type 1, a single intravenous injection of AAV8 carrying the paired CRISPR-Cas9 nickases system targeting the Hao1 gene in hepatocytes resulted in efficient and safe gene disruption and a significant therapeutic effect." (PMID 38182795, 2024).
breast carcinoma (4 papers, 2022 to 2025). "Breast cancer cells induced HAO1 expression and oxalate accumulation in alveolar epithelial cells by activating TLR3-IRF3 signaling." (PMID 35739335, 2022). "We also found that pharmacological inhibition of TLR3 abolished breast cancer-induced HAO1 expression and oxalate production." (PMID 35739335, 2022). "In this study, we show that metastatic breast cancer cells induce HAO1 expression in alveolar epithelial cells by activating TLR3-IRF3 signaling, rendering an over-production of oxalate." (PMID 35739335, 2022). "RNA-Seq analyses showed that HAO1-induced oxalate accumulation enhanced the proliferation of breast cancer cells mainly by activating MAPK signaling." (PMID 35739335, 2022). "In this study, we found that metastatic breast cancer elevated HAO1 expression in lung alveolar epithelial cells, which led to oxalate accumulation in the lung PMN." (PMID 35739335, 2022). "For instance, research indicates that hydroxyoxidase 1 (HAO1), the rate-limiting enzyme for oxalate synthesis, is significantly upregulated in mouse alveolar epithelial cells harboring metastatic breast cancer cells, resulting in abnormal accumulation of oxalate in lung tissue." (PMID 40342932, 2025). "Notably, pharmacological inhibition of HAO1 effectively blocked the lung oxalate accumulation induced by primary cancer, thereby significantly reducing lung metastasis of breast cancer." (PMID 40342932, 2025). "Extended analysis in the METABRIC (n = 1980) and Breast Cancer Gene-Expression Miner (n = 4421) transcriptomic databases and the Nottingham (n = 952) BC tissue cohort showed a varied survival outcome for HAO1 expression at the genomic, transcriptomic, and proteomic levels." (PMID 39519124, 2024). "Pharmacologic inhibition of HAO1 could effectively suppress the lung oxalate accumulation induced by primary cancer, consequently dampening lung metastasis of breast cancer." (PMID 35739335, 2022). "Here, we showed that hydroxyacid oxidase 1 (HAO1), a rate-limiting enzyme of oxalate synthesis, was upregulated in the alveolar epithelial cells of mice bearing metastatic breast cancer cells at the pre-metastatic stage, leading to oxalate accumulation in lung tissue." (PMID 35739335, 2022). "We investigated the role of TLR3 signaling in the upregulation of HAO1 in alveolar epithelial cells and found that TLR3 signaling was required for HAO1 expression in alveolar epithelial cells induced by primary breast cancer." (PMID 35739335, 2022). "Interestingly, we found that orthotopic implantation of metastatic breast cancer cell lines upregulated HAO1 expression only in lung PMNs, but not in brain, bone or liver PMNs." (PMID 35739335, 2022).
primary hyperoxaluria (4 papers, 2014 to 2022). A hereditary disorder characterized by excessive oxalate production, leading to hyperoxaluria. "A siRNA developed for the treatment of primary hyperoxaluria was designed to target the hydroxyacid oxidase 1 gene (HAO1), which encodes glycolate oxidase, a key enzyme in oxalate synthesis." (PMID 35326738, 2022). "Human HAO1 was recently proposed as a target for treating primary hyperoxaluria, an autosomal metabolic disorder leading to decline in renal function." (PMID 34555022, 2021).
lung carcinoma (3 papers, 2016 to 2024). "This activation promotes the proliferation of metastatic cancer cells, highlighting HAO1’s role in facilitating tumour growth in lung cancer." (PMID 39519124, 2024). "In lung cancer, hydroxyacid oxidase-1 (HAO1) is upregulated and results in oxalate accumulation." (PMID 39163890, 2024).
diabetes (2 papers, 2019 to 2023). "Amongst the top ranked new associations were IDUA and HAO1, representing two biological pathways of possible interest for diabetes: breakdown of glycosaminoglycans and 2-hydroxyacid oxidase activity." (PMID 31446444, 2019). "Twenty-six proteins were positively associated with diabetes, including cathepsin D, retinal dehydrogenase 1, α-l-iduronidase, hydroxyacid oxidase 1 and galectin-4 (top five findings)." (PMID 31446444, 2019).
hepatocellular carcinoma (2 papers, 2022 to 2024). A malignant tumor that arises from hepatocytes. "We then explored whether primary colorectal cancer (CRC) and hepatocellular carcinoma (HCC) could regulate HAO1 expression in the lung PMN." (PMID 35739335, 2022).
breast tumour (1 paper, 2024). "HAO1 protein expression was predominantly observed in the cytoplasm of invasive breast tumour cells, with expression levels ranging from absent to high." (PMID 39519124, 2024).
ductal carcinoma (1 paper, 2024). "Within the histological types, lobular carcinoma (pure or mixed) showed the most HAO1 CN gain (15/237 6.3%), while HAO1 CN loss (142/1544, 9.2%) was more common in ductal carcinoma (p = 0.007)." (PMID 39519124, 2024). "HAO1 protein was associated with ductal carcinoma (p = 0.0006)." (PMID 39519124, 2024).
glioma (1 paper, 2021). A benign or malignant brain and spinal cord tumor that arises from glial cells (astrocytes, oligodendrocytes, ependymal cells). "A genome-wide association study suggested that increased European ancestry in non-European population might be associated with the occurrence of glioma and identified four novel susceptibility variants, including 7q21.11 (SEMA3A), 11p11.12 (Intergenic), 12q24.21 (RBM19) and 20p12.13 (HAO1, BMP2)." (PMID 33430813, 2021).
Hyperoxaluria (1 paper, 2024). Increased excretion of oxalates in the urine. "Targeted therapy of the HAO1 gene holds promise for addressing hyperoxaluria." (PMID 38297313, 2024).
invasive breast carcinoma (1 paper, 2024). A carcinoma that infiltrates the breast parenchyma. "This study explored the prognostic significance of HAO1 expression at various molecular levels—gene CN, mRNA, and protein—and its relationship with clinical outcomes in invasive breast cancer, especially in ER+ subtypes." (PMID 39519124, 2024).
nephrocalcinosis (1 paper, 2024). Nephrocalcinosis is a disorder that occurs when too much calcium is deposited in the kidneys. "In this study, we demonstrated that a sustained reduction of GO protein expression could be achieved in PH1 mice through the administration of an AAV vector carrying both SaCas9 and Hao1-specific gRNAs, resulting in the reduction of oxalate production and prevention of nephrocalcinosis." (PMID 38182795, 2024).
Sepsis (1 paper, 2021). Sepsis is defined as life-threatening organ dysfunction caused by a dysregulated host response to infection. "Among that, Lrp5, Cyp7a1, Nfkbiz, Sigmar1, Fabp7, and Hao1 have been reported in the inflammatory response and lipid metabolic process, suggesting that these genes may play an important role in modulating sepsis-induced system inflammation in WT and LBP-deficient rats after LPS injection." (PMID 35005033, 2021).
tumor (60 papers, 2016 to 2026). "High HAO1 expression was significantly associated with high tumour grade (p = 0.002), which was primarily due to the association with high mitotic frequency (p = 0.0001) and pleomorphism (p = 0.001)." (PMID 39519124, 2024). "Within the PAM50 subtypes, luminal B tumours were more likely to have an HAO1 gene CN variation but curiously showed either loss or gain of HAO1 (p = 0.001)." (PMID 39519124, 2024). "Many tumours exhibited a normal HAO1 gene CN, with only 165/1980 cases (8.3%) showing an HAO1 gain and 28/1980 cases (1.4%) displaying a CN loss." (PMID 39519124, 2024). "HAO1 CN gain also predicted poor overall survival for tumours that were ER+, ER+/PR+, and ER+/PR− (p = 0.002, p = 0.040 and p = 0.018, respectively) but not in ER negative tumours (p = 0.998)." (PMID 39519124, 2024). "In this study, we show that patients with ER+ tumours and a higher expression of HAO1 have predicted shorter DMFS." (PMID 39519124, 2024). "Compared to the normal tissue in the TCGA cohort, ACOX2 (P < 0.001), PTGS1 (P < 0.001), PTGS2 (P < 0.001), and PPARGC1A (P < 0.001) were downregulated, while HAO1 (P < 0.001) was upregulated in tumor samples." (PMID 38706909, 2024). "We thus applied CCPST to block the function of HAO1 in tumor-bearing mice." (PMID 35739335, 2022). "To examine whether exosomes were involved in tumor-induced HAO1 expression, we derived exosomes from 67NR and 4T1 cells for further study." (PMID 35739335, 2022). "Although a gain in HAO1 CN was observed in some tumours, it did not correlate with higher HAO1 mRNA expression, suggesting that other regulatory mechanisms are involved." (PMID 39519124, 2024). "In multivariate analysis, HAO1 protein was a prognostic factor independent of tumour size, nodal stage, and grade in ER+ tumours." (PMID 39519124, 2024). "HAO1 immunoreactivity in full-face breast tissue sections showed homogenous staining of invasive BC cells, indicating that TMA cores were representative of the whole tumour." (PMID 39519124, 2024). "Moreover, we observed a higher expression of HAO1 in alveolar epithelial cells in lung tissue sections from 4T1-bearing mice showed compared with those in mice without tumor." (PMID 35739335, 2022).
cancer (33 papers, 2016 to 2025). A tumor composed of atypical neoplastic, often pleomorphic cells that invade other tissues. "Targeting HAO1-mediated oxalate metabolism is a feasible approach to prevent and treat cancer metastasis to the lung." (PMID 35739335, 2022). "The results showed that both CCPST and HAO1 knockdown suppressed oxalate production in lung PMN induced by primary cancer." (PMID 35739335, 2022). "Collectively, these findings underscore the role of HAO1-mediated oxalate metabolism in cancer-induced lung PMN formation and metastasis." (PMID 35739335, 2022). "The accumulation of oxalate via HAO1 could alter the redox state and overall metabolic environment of cancer cells, potentially modulating SLC activity or being regulated by the metabolic changes they induce." (PMID 39519124, 2024). "Finally, we explored the mechanism by which primary cancer induces HAO1 expression in alveolar epithelial cells." (PMID 35739335, 2022). "However, the functional role of HAO1-mediated oxalate metabolism in cancer development remains unclear." (PMID 35739335, 2022). "Then, we evaluated whether inhibition of HAO1 could be used to prevent lung metastasis of cancer." (PMID 35739335, 2022). "HAO1 could be an appealing therapeutic target for preventing lung metastasis of cancer." (PMID 35739335, 2022). "UROC1 (21%), HAO1 (15%), and SLC5A5 (14%) were the top three mutant genes in human cancers." (PMID 36313638, 2022).
metabolic disease (2 papers, 2020 to 2021). A congenital disorder (due to inherited enzyme abnormality) or acquired (due to failure of a metabolically important organ) disorder resulting from an abnormal metabolic process. "Most importantly, our data support the potential safety of HAO1 inhibition as a chronic therapy for the devastating metabolic disease PH1." (PMID 32207686, 2020).
immune diseases (1 paper, 2024). "In addition, genes related to immune diseases (e.g., BID, SMARCD3, ATP6V1E1, NFKB2), energy metabolism (e.g., HAO1, NDUFA7, CERS4, MTHFD1), and other factors were also screened." (PMID 38750582, 2024).
HAO1 also shares sentences with these, for which no sentence is quoted: infection (5 papers); Hyperglycemia (3); amyloidosis (1); colorectal cancer (1); endometriosis (1); endothelial dysfunction (1); kidney damage (1); kidney stone (1); lobular carcinoma (1); melanoma (1); neuroblastoma (1); ovarian carcinoma (1); prostate adenocarcinoma (1); type II xanthinuria (1).